CDKN1C (cyclin dependent kinase inhibitor 1C)
Diseases named in the same sentence as CDKN1C in open-access papers (continued):
Sharing a sentence is not in itself a finding about the gene and the disease.
tumor (continued). "CDKN1C promoter DNA hypermethylation is the most common mechanisms, and inhibition of DNA methylation indeed increases p57KIP2 expression and impairs tumor growth." (PMID 38561743, 2024). "In contrast, CDKN1B and CDKN1C are cyclin-dependent kinase (CDK) inhibitors, p27Kip1 and p57Kip2 respectively, that usually act as tumor suppressors, but their regulation is altered during tumor processes, leading to unchecked cellular proliferation." (PMID 39336170, 2024). "The role of CDKN1C as a cell cycle inhibitor and its observed downregulation in many cancers has led to its designation as a tumor suppressor gene (TSG)." (PMID 37035141, 2023). "CDKN1C, a cyclin‐dependent kinase inhibitor, was significantly upregulated by PIK3R3 knockdown, and CDKN1C siRNA rescued the impaired tumor cell growth." (PMID 37212524, 2023). "The 1° tumor had eight variants in MKI67, PRKN, PCLO, POLE, CDKN1C, IGSF3, and MED12 genes, which were also present in the brain and spine metastatic cell lines but not present in the parental cell line." (PMID 36900209, 2023). "Among HB without mosaicism, tumors with 11p15.5 alteration showed a higher IGF2 expression (P = 0.01) and a lower H19 and CDKN1C tumor suppressor expression (P = 5.3 x 10−8 and P = 4.0 x 10−3, respectively)." (PMID 37932266, 2023). "In conclusion, we have discovered a new, acquired vulnerability in NSCLC associated with LKB1/STK11 mutations in a subset of NSCLCs that is represented by GR agonist induced CDKN1C expression leading to a host of anti-tumor responses." (PMID 37035141, 2023). "In conclusion, knockdown PIK3R3 inhibits the tumor growth of HCC by upregulating the expression of CDKN1C and downregulating the expression of SMC1A by deactivating the Akt pathway and inhibiting cell proliferation and colony formation." (PMID 37212524, 2023). "When administered in combination therapy with the HDAC inhibitor SAHA, JQ1 induces expression of the P57 (CDKN1C) tumor suppressor in mouse pancreatic ductal adenocarcinoma, which correlates with increased acetylation of histone H3 tails at the P57 promoter." (PMID 35399501, 2022). "This tumour rate in patients with BWSp with CDKN1C abnormalities is similar to rates reported in previous series." (PMID 35954470, 2022). "It is noteworthy that with augmentation in CDKN1C expression, the tumour purity was significantly lower, indicating higher levels of TIICs." (PMID 34464504, 2021). "Precise regulation of CDKN1C is imperative for embryogenesis, differentiation, as well as tumour suppression." (PMID 34272384, 2021). "We observed significant upregulation of the caspase 8 (CASP8) gene which is responsible for the apoptotic pathway and CDKN1C which is a tumor suppressor gene." (PMID 34885223, 2021). "The results showed that the growth rate and weight of tumor decreased significantly, the expression of CDKN1C was increased and CCNE was decreased after silencing BLACAT1, but reversed under up-regulating BLACAT1 treatment." (PMID 33072570, 2020). "The CDKN1C, which is also known as p57kip2, is claimed to be a tumor suppressor considered to be a potential tumor suppressor caught up in several types of cancer in humans." (PMID 32318583, 2020). "It suggested that interference with BLACAT1 can up-regulate CDKN1C expression and inhibit tumor growth in vivo." (PMID 33072570, 2020). "The CDKN1C gene produces the cyclin-dependent kinase inhibitor p57, which functions as a tumour suppressor in multiple cancer types." (PMID 30791601, 2019). "Of the 22 upregulated genes, obASCs upregulated estrogen-related genes that have been shown to promote tumor growth, such as ESR2; as well as cell-cycle-related genes associated with proliferation, such as CDKN1C and CDKN2A." (PMID 30897853, 2019).
tumor (continued). "We also performed Western blot analyses to detect the levels of CDYL, EZH2, and CDKN1C in xenograft tumours, and GSK126 significantly increased CDKN1C levels in CDYL-overexpressing H69 cells, but did not significantly change CDYL levels." (PMID 31367252, 2019). "Collectively, CD271 initiates tumor formation by increasing the cell proliferation capacity through CDKN1C suppression and ERK-signaling activation, and by accelerating the migration signaling pathway in HPC." (PMID 27469492, 2016). "As member of the Polycomb-group family, EZH2 acts as transcription repressor of several cell cycle-related tumor suppressor genes such as CDKN1C through methylation of histone H3 on lysine 27 (H3K27)." (PMID 26110843, 2015). "This resulted in the up-regulation of EZH2-silenced tumor suppressor genes, including CDKN1C, DAB2IP, and WNT5a, in a dose-dependent manner in multiple cancer cell lines (e.g., T24, MBT2, and PC3)." (PMID 25431950, 2014). "The cyclin-dependent kinase inhibitor 1C has an impact on cell proliferation and acts as a tumor suppressor gene." (PMID 22701369, 2012). "Targeting EZH2-H3K27me3 by DZNep would presumably synergize with HDAC inhibitors and/or Aza to maximally restore the tumor suppressor function of CDKN1C." (PMID 19340297, 2009). "However, CD40, glypican 3 (GPC3), Iroquois homeobox 2 (IRX2), FOXO1, EPAS1, and cyclin-dependent kinase inhibitor 1C (CDKN1C) were consistently down-regulated in tumor tissues and GbPDTOs compared to those in normal tissues." (PMID 41376821, 2025). "Loss of mitosis in tumor cells is associated with a marked reduction in cyclin-dependent kinase (CDK1) transcription and/or loss of its active form (CDK1-P-Thr 161), which coincides with upregulation of CDKN1A, CDKN1B, and CDKN1C." (PMID 39766809, 2024). "Additionally, the lncRNA KCNQ1OT1 regulates the imprinted expression of the KCNQ1 and CDKN1C genes, both showing tumor suppressor activity in several tumors, including CRC." (PMID 37046605, 2023). "Thus, the association of imprinted genes (e.g., CDKN1C, IGF2) with growth and tumor risk is emerging." (PMID 37440461, 2023). "Firstly, CDKN1C+ CAFs within the PD-L1 + TME may transition into a suppressive state through interactions with PD-L1+ tumor or immune cells, as well as other cells commonly found in an inflamed TME, such as plasma cells and dendritic cells." (PMID 37696887, 2023). "In PCa, CDKN1C was shown to have a tumor suppressor role and was inhibited by the oncogenic miR‐21." (PMID 35612714, 2022). "In addition, qRT-PCR and western blotting results showed that miR-92b-3p and CDKN1C had similar expression profiles in xenograft tumor models as in CRC cell models." (PMID 34283053, 2021). "Moreover, treatment of tumor cell lines with demethylating agents such as 5-aza-2′-deoxycytidine resulted in CDKN1C expression activation." (PMID 34789717, 2021). "Furthermore, correlation between CERES accessibility and CDKN1C expression was found to be dependent on GR mRNA levels and increased in a step-wise manner with the removal of tumour samples with the lowest GR expression levels." (PMID 34272384, 2021). "More understanding of the regulatory role of CDKN1C in apoptosis, especially in the chemotherapy setting, may provide more clarity on the mechanisms of drug resistance in tumor cells and bring new insights to clinical treatment." (PMID 34283053, 2021). "We further explore the implication of CDKN1C in biological function and tumour immune infiltration." (PMID 34464504, 2021). "The antisense transcript LIT1 originating from the CDKN1C tumor suppressor locus on Chr." (PMID 29861427, 2015).
tumor (continued). "Three independent ChIP analyses each, on both F22 and STMpc rhabdoid tumor cell lines, showed that the CDKN1C promoter is acetylated in un-induced F22 and STMpc cells, however histone H3 acetylation increased 2 fold in both cell lines following SMARCB1 induction with 4HT." (PMID 19221586, 2009). "Combining these data with existing knowledge of the gene's regulation and the protein's function, suggest that CDKN1C is a tumor suppressor that could act early in breast carcinogenesis, perhaps in the myoepithelial compartment." (PMID 18325103, 2008). "AI/LOH of the 11p15.4-5 region in general and decreased expression of CDKN1C was not clearly associated with tumor grade, histology, ER, PR or HER2 status." (PMID 18325103, 2008). "Another factor that might affect the precise estimation of the tumour risk in patients with BWSp and CDKN1C variants could be related to the lack of diagnoses during adulthood or clinical management until their adolescent/early adult life." (PMID 35954470, 2022). "Interestingly, we found that alterations in specific CNV regions in LMS affected the expression of CDKN1C, a cyclin/Cdk inhibitor that may act as a tumor suppressor." (PMID 35216305, 2022). "However, whether CDKN1C is also involved in the MDR of tumor cells, and its role and mechanism in the MDR of CRC cells remain unclear." (PMID 34283053, 2021). "Notably, in E-SOBP cells, we observed upregulation CASP8 molecular switch for apoptotic pathway, the anti-proliferative tumor regulator CDKN1C, and tumor suppressor and Ras Suppressor Protein 1, which is also a strong tumor suppressor gene in E-SOBP treated cells." (PMID 34885223, 2021). "However, although all samples in the exploratory cohort exhibited significant downregulation of this gene, only two tumours exhibited high levels of hypermethylation (521 and 840), suggesting additional mechanisms to explain CDKN1C downregulation in the remaining samples." (PMID 29661169, 2018). "Decreased CDKN1C was not clearly associated with tumor grade, histology, ER, PR or HER2 status." (PMID 18325103, 2008). "Some tumor suppressor genes, e.g., RB1 and CDKN1C, can be downregulated or inactivated in cancer via promoter hypermethylation or copy number loss, inactivating mutations in RB1 or imprinting allele switching of CDKN1C." (PMID 40414875, 2025). "CDKN1C inhibits proliferation and CASP1 mediates pyroptosis—a form of cell death triggered by proinflammatory signaling, thus representing tumor suppressor genes." (PMID 38474011, 2024). "We found that PIK3R3 upregulated the expression of CDKN1C, downregulated the expression of SMC1A, and activated Akt signaling, thereby promoting HCC cell proliferation and tumor growth." (PMID 37212524, 2023). "The expression of miR-222 was significantly up-regulated in the muscle tumor tissues, while the expression levels of two target genes of miR-222, cyclin-dependent kinase inhibitor 1B (CDKN1B) and CDKN1C, were down-regulated in the tumors." (PMID 36497250, 2022). "These gain‐ and loss‐of‐function experiments in vitro and analysis of available human tumor datasets suggest a functional relationship between HES1, YAP1, and CDKN1C in FN‐RMS, with both HES1 and YAP1 upstream of CDKN1C." (PMID 36037042, 2022). "We also presented evidence that GR-mediated regulation of CDKN1C by the CERES enhancer occurs in clinical samples, highlighting the relevance of this regulation in tumour development and progression." (PMID 34272384, 2021). "Five of these signaling proteins (CDKN1B, CDKN1C, PTN, GJA1, and MORF4L2) can act as tumor suppressors." (PMID 32168333, 2020).
tumor (continued). "These genes are localised close to known cyclin-dependent kinase inhibitors and tumour suppressors CDKN1C and CDKN2A/B, respectively, but both FAF1 and MTAP have recently been proposed to harbour tumour suppressor activity in their own right." (PMID 24548782, 2014). "Analysis of cell cycle pathway in KEGG of each differential list of genes showed that in normal lung tissue only tumor suppressor genes (CDKN1A/p21, CDKN1C/p57, RBL2/p130) and the cyclin D family were overexpressed, reflecting a normal phenotype." (PMID 25325012, 2014). "The ΔCt between CDKN1C and GUSB for each normal sample was compared to its paired tumor sample to generate the relative expression of CDKN1C mRNA between tumor and normal." (PMID 18325103, 2008). "Given the tumor-suppressive roles of CDKN1B and CDKN1C, miR-222-mediated down-regulation of CDKN1B and CDKN1C may contribute to Ni-induced tumorigenesis or tumor progression." (PMID 36497250, 2022). "Cyclin-dependent kinase inhibitor 1C (CDKN1C, also known as p57(KIP2)), a tumor suppressor, could regulate tumor cell differentiation, invasion, and angiogenesis, which is also validated as a prognostic biomarker in various cancer types, including in LIHC." (PMID 35733217, 2022). "Consequently, we established a nomogram incorporating the CDKN1C expression, age, TNM staging and tumour subtype aiming to predict the OS in BC patients." (PMID 34464504, 2021). "Besides, based on the immunohistochemical detection results of CDKN1C and CCNE expression in tumor tissue, and it was discovered that in comparison with sh-NC group, the expression of CDKN1C was highly increased and CCNE was decreased in sh-BLACAT1 group." (PMID 33072570, 2020). "At the same time, tumor-suppressive genes such as MT1G, MT1M, CDKN1C, and DCN were overexpressed." (PMID 30568916, 2018). "However, it is important to note that IC2 methylation and KCNQ1OT1 imprinting were similarly relaxed in the neoplastic and peri-neoplastic tissues, and KCNQ1 and CDKN1C were not repressed in the tumor with respect to normal tissue in our patient." (PMID 37046605, 2023). "Significantly and perhaps not surprisingly we found that CDKN1C expression was absent from the clinical tumor specimens we examined, of which the majority were CNS AT/RT, and our evidence from RT cell lines also supports an important role for CDKN1C in RT growth suppression." (PMID 19221586, 2009). "Finally, to determine whether there might be a relationship between HES1, YAP1, and CDKN1C in human tumor tissue, we examined their expression at the transcript and protein level (when available) in human RMS tumor samples by querying published databases generated for the RMS research community." (PMID 36037042, 2022). "As p57Kip2 (CDKN1C), a negative regulator of proliferation and a tumor suppressor, is controlled by members of the NAP1 family, we tested the hypothesis that NAP1L1 may have a mechanistic role in regulating pancreatic NEN proliferation through regulation of p57Kip2." (PMID 25071868, 2014).
cancer (94 papers, 2006 to 2026). A tumor composed of atypical neoplastic, often pleomorphic cells that invade other tissues. "Correlation analysis showed a strong association between CDKN1C, a key senescence marker, and HLA-E expression in HLA-E positive cancer cells (R > 0.5, p < 0.05)." (PMID 40959273, 2025). "Loss of p57 expression in human carcinomas is caused predominantly by loss of heterozygosity of the 11p15.5 locus, methylation of the CDKN1C promoter, and histone methylations." (PMID 33117811, 2020). "Among them, the main cause of reduction of p57Kip2 in cancers is generally the increased methylation of the large CpG islands localized in the CDKN1C promoter." (PMID 29614816, 2018). "This is consistent with the widespread inactivation of CDKN1C in many different cancers with additional oncogenic mutations and suggests that CDKN1C silencing contributes, but is alone insufficient, to cause tumors." (PMID 19221586, 2009). "Silencing of CDKN1C in cancer is usually epigenetic and associated with promoter methylation or histone deacetylation." (PMID 19221586, 2009). "CDKN1C (also known as p57KIP2) is a cyclin-dependent kinase inhibitor previously implicated in several types of human cancer." (PMID 18325103, 2008). "We found that cancer-associated fibroblasts (CAFs) are the main TME cells expressing CDKN1C." (PMID 37696887, 2023). "Deregulation of imprinting of the 11p15.5 locus, as well as loss of heterozygosity (LOH) or point mutations of CDKN1C are responsible for the development of several hereditary pathologies and may contribute to cancer development and progression." (PMID 33117811, 2020). "After OTX015 SCLC resistant and sensitive cells differed presenting an up-regulation of CDKN2D (P19) in resistant cells, and of CDKN1C (P57) in the sensitive cells, changes that could be linked with the different sensitivity to anti-cancer drugs." (PMID 27835869, 2016). "CDKN1C (encoding tumor suppressor p57KIP2) is a cyclin-dependent kinase (CDK) inhibitor whose family members are often transcriptionally downregulated in human cancer via promoter DNA methylation." (PMID 19340297, 2009). "Loss of myoepithelial CDKN1C protein expression could participate in the dysregulation of this process, resulting in cancer progression." (PMID 18325103, 2008). "Although the use of glucocorticoids as a long term maintenance therapy for cancer patients is less than ideal, a therapy capable of inducing CDKN1C expression is an attractive strategy not only because of strong growth inhibition but also because somatic inactivating mutations of CDKN1C are rare." (PMID 37035141, 2023). "The major mechanism of p57KIP2 downregulation in cancer is epigenetic chromatin modification of CDKN1C promoter." (PMID 38561743, 2024). "CDKN1C promoter contains numerous CpG islands that can be methylated, leading to inhibition of CDKN1C transcription, which is one of the main mechanisms of p57KIP2 inactivation in cancer." (PMID 38561743, 2024). "KCNQ1OT1/Kcnq1ot1, an lncRNA transcribed from the opposite strand of KCNQ1 within the CDKN1C/KCNQ1OT1 cluster, has been implicated as a critical factor in cancer development and progression." (PMID 39201613, 2024). "The authors of this study provide data showing that this cancer cell dormancy phenotype is due to the GR-induced expression of its target gene cyclin-dependent kinase inhibitor 1C (CDKN1C) through long-distance chromatin interactions." (PMID 37759686, 2023). "Understanding the role of CDKN1C in the regulation of cell cycle checkpoints and its relationship with cancer development is crucial for the development of targeted therapeutic strategies." (PMID 37174013, 2023).